APOE (apolipoprotein E)
Diseases named in the same sentence as APOE in open-access papers (continued):
Sharing a sentence is not in itself a finding about the gene and the disease.
Cognitive impairment (continued). "Additionally, a greater Cp burden was observed in APOE ε4 allele carriers, and this burden correlated with brain Cp load, AD pathological changes (e.g., brain NFTs, Braak, and ABC severity scores), and cognitive deficits (e.g., CDR, MMSE)." (PMID 40667156, 2025). "Moreover, a significant interaction was found between a more severe cognitive impairment and APOE ε4/ε4 genotype on CSF/serum λ FLC levels (F = 4.168, p = 0.004)." (PMID 39992249, 2025). "Additionally, we explored potential moderating effects of different PA dimensions on the relationship between APOE ε4 genotype and cognitive impairment." (PMID 39789564, 2025). "In addition, in the sub-group of adults with HF, APOE ε4 frequency was higher in participants with mild cognitive impairment and AD when compared with individuals with normal cognition, although this difference was not statistically significant." (PMID 40699836, 2025). "ApoE exhibits an injury-severity-dependent increase during the early stage of TBI, and its levels are closely associated with oxidative stress imbalance and cognitive impairment." (PMID 41394006, 2025). "We found no mediation by onset age of cognitive impairment in the association between APOE SNPs and anxiety or delusion in ADNI dataset." (PMID 39974048, 2025). "Maintaining activity levels from midlife to late life was also associated with lower cognitive impairment risk in APOE ε4 non-carriers (OR = 0.77, 95%CI = 0.59 ~ 0.99, P-value = 4.48 × 10− 2)." (PMID 39789564, 2025). "Additionally, a greater Cp burden was observed in APOE ɛ4 allele carriers, and this burden correlated with brain Cp load, AD pathological changes (e.g., brain NFTs, Braak, and ABC severity scores), and cognitive deficits (e.g., CDR, MMSE)." (PMID 40678205, 2025). "APOE ε4 carriers were younger at study entry (χ2 = 59.97, P = 4.43 × 10−14), were more likely to have cognitive impairment at baseline (χ2 = 138.32, P < 2.2 × 10−16), and were more likely to be longitudinal diagnosis converters (χ2 = 92.34, P < 2.2 × 10−16) compared to APOE ε4 non‐carriers." (PMID 39711105, 2025). "Data‐driven analysis was applied on demographic data, apolipoprotein E (APOE) ε4 allele, and 82 biomarkers obtained from blood tests of healthy controls (HC), mild cognitive impairment that remained stable within 36 months following blood collection (sMCI), and patients with AD." (PMID 41383880, 2025). "Further clinical studies within the ADNI database have shown that in females with mild cognitive impairment, increased uricemia may interact with apolipoprotein E4 (APOE4) to alleviate longitudinal metabolic changes and cognitive decline." (PMID 39976039, 2025). "Considering the additive effect of FSH and APOE ε4 in the development of AD-like pathogenesis in female mice, we investigated whether gonadotropins and APOE ε4 interact in cognition impairment." (PMID 41180813, 2025). "This meta-analysis confirms that WMHs, lacunes, CMBs, and the APOE ε4 allele are significantly associated with both early (MCI and GCI) and late (ACD, VaD, and AD) stages of cognitive impairment, reinforcing the concept of a vascular–neurodegenerative continuum." (PMID 41153256, 2025). "After controlling for variables such as sex, age, education years, and APOE ε4 genotype, the presence of HV+ and FDG (IP)+ significantly increased the risk of cognitive impairment within the A+T+ subgroup, with the risk associated with HV+ being particularly pronounced." (PMID 39989286, 2025). "The T2DM patients carrying the ApoE ε4 allele exhibit heightened activation of platelet glycogen synthase kinase‐3β (GSK‐3β), a key downstream kinase in the insulin signaling pathway, along with more severe cognitive deficits." (PMID 40905109, 2025). "The ε4 allele of the apolipoprotein E (APOE) gene is a predominant genetic risk factor for AD, with APOE4 being associated with detrimental effects on various neurodegenerative conditions linked to cognitive impairment, including AD." (PMID 40003632, 2025).
Cognitive impairment (continued). "Hence, results are not inconsistent with previous findings that amyloid positivity in APOE‐ε4 carriers is much more likely to progress to cognitive impairment than it is in non‐carriers." (PMID 40018326, 2025). "Therefore, this study aims to investigate the role of HIIT and CBD supplementation in ameliorating cognitive impairment in a rat model of Aꞵ-induced AD via targeting APOE, presenilin-1, and glutamate." (PMID 39539449, 2024). "The lack of ApoE association with cognitive deficits in PD in another study was attributed to the early disease stage of that cohort." (PMID 38988604, 2024). "Compared to individuals without APOE e4 allele or loneliness, those with the APOE e4 allele only were three times more likely to experience cognitive impairment." (PMID 38962235, 2024). "Therefore, the present study raises the possibility that HIIT combined with CBD administration can alleviate cognitive impairment by regulating the expression of APOE, presenilin-1, and glutamate proteins in a rat model of AD induced by ꞵ-amyloid." (PMID 39539449, 2024). "Therefore, it is imperative for future studies to investigate the impact of ApoE ε4 genotype and olfactory dysfunction on the onset of cognitive impairment in a larger population with a longer follow-up period." (PMID 38660514, 2024). "Accordingly, the present study sheds new light on the emerging role of HIIT combined with CBD supplementation in improving AD progression via modulating the expression of APOE, presenilin-1, and glutamate proteins, reducing Aꞵ plaque, apoptosis, and decreasing cognitive impairment." (PMID 39539449, 2024). "In this study, we examined the effect of APOE ε4 on synaptic density in individuals with cognitive impairment by using SV2A PET and tested whether APOE ε4 has diverse effects on subfields of the hippocampus." (PMID 38477490, 2024). "Females who are carriers of the APOE ε4 allele exhibited the most pronounced cognitive deficits compared to their male counterparts and non-carriers." (PMID 39886338, 2024). "Research on the APOE-IR relationship has largely focused on insulin and cardiovascular disease mechanisms in APOE knockout mice, as well as the effect of APOE gene variations on brain insulin metabolism in human cognitive impairment." (PMID 38956564, 2024). "Moreover, the epsilon 4 isoform of apolipoprotein-E (APOE-ε4) has been associated with both sporadic and familial late-onset AD, and patients with mild cognitive impairment (MCI) due to AD are more likely to progressively deteriorate." (PMID 38392625, 2024). "The relationship between APOE ε4 genotype and cognitive impairment is well studied." (PMID 39639910, 2024). "Another research that used the Women's Health Initiative Memory Study (WHIMS) data found that exposure to a high level of PM2.5 preceded onset of cognitive impairment in older women, and this relationship varied by APOE genotype, with the largest adverse effect seen in e4/e4 carriers." (PMID 39135618, 2024). "Furthermore, hub vulnerability manifests even in individuals at high risk for AD, such as patients with mild cognitive impairment (MCI), carriers of the Apolipoprotein E epsilon 4 allele (APOE ɛ4), and cognitively healthy elderly with preclinical AD." (PMID 39281195, 2024). "The current study examined whether APOE is associated with the rate of cognitive change in SCD and mild cognitive impairment (MCI)." (PMID 38253819, 2024). "The APOEε4-specific association of ANGPTL4 with future cognitive impairment may be driven by the joint role of ANGPTL4 and APOE in lipid metabolism." (PMID 39482741, 2024). "Association between multiple lifestyle factors and cognitive impairment in participants without the APOE ε4 gene." (PMID 39639910, 2024).
Cognitive impairment (continued). "Furthermore, thrombin delivered directly into the brain via intracerebroventricular injection results in significant neuropathology, enlargement of cerebral ventricles, increased TUNEL-positive cells, astrogliosis, ApoE fragments, and cognitive impairments." (PMID 37174621, 2023). "In addition to neurodegeneration, other factors also contribute to clinical cognitive impairment, such as years of education, hearing impairment, and APOE genotype." (PMID 36864910, 2023). "An article published with the preliminary results of our study did not reveal an association between cognitive impairment and APOE." (PMID 38137059, 2023). "We detected recurring polymorphisms on chromosome 19 in the non-coding region upstream of the APOC1 gene (rs10414043) and in the APOE gene (rs429358 and rs769449) and identified a possible mechanism whereby these substitutions contribute to cognitive impairment." (PMID 37953886, 2023). "Their inclusion in studies has undoubtedly increased understanding of biomarkers for cognitive function and cognitive disorder, in this case, demonstrating that individual differences, such as APOE phenotypes, may have survival and development benefits." (PMID 37371340, 2023). "An interactive effect of WMH and the APOE e4 gene on clinical cognitive impairment has been reported by some studies; however, the exact mechanism or etiology remains unclear." (PMID 36864910, 2023). "When controlling for other NPSs, MBI‐psychosis was no longer associated with a higher rate of incident cognitive impairment in APOE ε4 non‐carriers (HR: 0.9, 95% CI: 0.4–2, p = 0.8)." (PMID 37139261, 2023). "Our results support that microglial P2X4 promotes lysosomal ApoE degradation, indirectly altering Aß peptide clearance, which in turn might promotes synaptic dysfunctions and cognitive deficits." (PMID 37145189, 2023). "Apolipoprotein E polymorphism ε4 (APOE ε4) and methylenetetrahydrofolate reductase (MTHFR) TT genotype are genetic risk factors of mild cognitive impairment (MCI), but whether this risk can be changed by modifiable lifestyle factors is unknown." (PMID 37462970, 2023). "In this context, the enlargement of CP volume with female sex, cognitive impairment and ApoE E4 could represent a specific, yet largely independent, pro-inflammatory signature." (PMID 36970283, 2023). "In addition, we aimed to investigate the relationship between APOE ε4 and cognitive impairment while considering the impact of other factors." (PMID 38026513, 2023). "Additionally, the APOE ε3 R136S (Christchurch) variant (APOE-Ch) has been found to protect against an EOAD PSEN1 mutation, delaying cognitive impairment and reducing tau pathology despite high levels of Aβ." (PMID 37986179, 2023). "However, after the disease onset, the effect of the APOE genotype on the progression of cognitive impairment remained debated." (PMID 38132357, 2023). "Given that the GSK‐3β activity can be regulated by ApoE in vitro, we hypothesize that the activation of GSK‐3β may play a mediative role between ApoE ε4 and cognitive impairment in T2DM patients." (PMID 37700547, 2023). "Potential Confounding Variables: The study mentioned several risk factors associated with disease progression, such as apolipoprotein E4 (APOE-e4), depression, loneliness, hearing impairment, diabetes, hypertension, older age, female gender, and cognitive impairment." (PMID 38156089, 2023). "GSK‐3β activation acts as a mediator between ApoE ε4 and cognitive impairment." (PMID 37700547, 2023). "We found that incarceration imparted risk for cognitive impairment in later life that was independent of and comparable to the leading genetic risk factor (APOE-ε4)." (PMID 38048316, 2023). "The estimated duration of preclinical AD is approximately 10 years, but it depends on several factors including age and apolipoprotein E genotypes, while the prodromal stage with amyloid accumulation and diagnoseable mild cognitive impairment is approximately four years." (PMID 37016409, 2023).
Cognitive impairment (continued). "APOE‐ε4 and mild cognitive impairment were associated with higher cortical iron in a neuroimaging study using a 7.0T QSM, which may suggest iron leakage by impaired BBB in an APOE‐ε4 carrier." (PMID 37377861, 2023). "We hypothesized that subjects with AD and mild cognitive impairment (MCI) would have reduced CSF CEC compared with Cognitively Normal (CN) and that CSF apolipoproteins apoA-I, apoJ, and apoE might have associations with CSF CEC." (PMID 36572909, 2022). "Combined with the results of the present study, disordered APOE-mediated clearance of remnant lipoprotein might partly participate in the development of cognitive impairment." (PMID 36376895, 2022). "Our results further strengthen the findings of a recent meta-analysis including 25 independent studies, showing that APOE ε4-carriers who were also KL-VSHET+, were at a reduced risk for the combined outcome of conversion to mild cognitive impairment (MCI) or AD." (PMID 35617280, 2022). "In PD, APOE ε4/ε4 conferred a two-fold risk of cognitive impairment compared to one or no ε4 (HR: 2.09 (95% CI: 1.13–3.89; p = 0.02)), while APOE ε2 was associated with modest protection against cognitive impairment (HR: 0.41 (95% CI 0.19–0.99, p = 0.02))." (PMID 36371506, 2022). "To date, the link between APOE and PD risk and age at onset or PD related cognitive impairment has not been explored in individuals of black African ancestry within or outside Africa." (PMID 36371506, 2022). "Additionally, miRNA analysis identified hsa-miR-107 as a possible biological link between APOE ε4, depressive symptoms, and cognitive impairment." (PMID 35884866, 2022). "Cognitive impairment in patients with COVID-19 does not necessarily involve specific APOE polymorphisms." (PMID 36046159, 2022). "As in our study, others have shown strong Aβ accumulation in a clinical case with resistance to familial AD in correlation with an APOE3 mutation in homozygosis, which led the authors to propose that reduced ApoE activity is likely to prevent cognitive deficits." (PMID 35254651, 2022). "Therefore, future studies examining the influence of APOE ε4 on sex differences in MMP-9 associations with AD pathology and cognitive impairment are warranted." (PMID 36324151, 2022). "We discovered that a lack of total ApoE did not prevent the phosphorylation of Tau or the development of cognitive impairment caused by sevoflurane anesthesia." (PMID 35810473, 2022). "Besides cross-sectional studies, a longitudinal study by Altmann el al., which focused on the speed at which healthy people convert to cognitive impairment during aging, also demonstrated a stronger effect of APOE ε4 on women." (PMID 35149974, 2022). "Apolipoprotein E (ApoE) may mediate general anesthetic-induced neuronal toxicity and cognitive impairment in the developing brain." (PMID 36504660, 2022). "Non-drinkers with at least one APOE Ɛ4 allele demonstrated a 35% increased risk of later life moderate cognitive impairment as compared to non-drinkers with no copies of the Ɛ4 allele (HR = 1.352, CI = 1.04-1.75)." (PMID 35275952, 2022). "Compared to respondents without an APOE Ɛ4 allele, those with at least one copy showed an increased risk of cognitive impairment at all levels of midlife alcohol consumption." (PMID 35275952, 2022). "We used acquired (COVID-19 infection) and non-modifiable (presence of APOE rs429358 and rs7412 polymorphisms) factors to study the progression of subjective cognitive impairment while observing patients for one year." (PMID 36292001, 2022). "Neurotoxicity and cognitive impairment in mice exposed to sevoflurane may be related to the expression of ApoE and its toxic fragments." (PMID 36504660, 2022). "We used ApoE3 and ApoE2‐targeted replacement mice in our present investigation to examine whether full‐length ApoE or ApoE fragments played a role in the development of Tau phosphorylation and cognitive impairment in young mice under sevoflurane anesthesia." (PMID 35810473, 2022).
Cognitive impairment (continued). "The ApoE ε4 effects on the brain are also macroscopically detected since it has proved to be related to hippocampal atrophy in subjects affected by mild cognitive impairment (MCI), and the presence of the ApoE ε4 genotype seems to be linked to a faster decline in memory tests." (PMID 36358488, 2022). "The associations of cognitive impairment with smoking, alcohol consumption, physical activity, dietary pattern, and body weight did not vary by APOE genotype (all Ps > 0.05)." (PMID 34061824, 2021). "Second, owing to the cross-sectional study design, the causality between ApoE rs429358, ApoA1 and ApoB levels, and cognition impairment in patients with schizophrenia was not directly revealed." (PMID 34135129, 2021). "Genetic factors, such as mutation carriers (amyloid precursor protein, presenilin, and asynuclein) and apolipoprotein E (APOE) ε4 carriers, may be useful in determining the etiology of cognitive impairment." (PMID 34073323, 2021). "Furthermore, repeated 9D11 injections showed the formation of ApoE/IgG complexes that reversed the cognitive impairments compared to the control ApoE4 mice, indicating a potential reversal of cognitive impairment." (PMID 33513969, 2021). "Cognitive impairment during the 3 month post-ICH time period was also associated with increased hematoma volume—hazard ratio [(HR) 1.52 per 10 cc increase], and APOE ε2 genotype (HR: 1.69), prior history of stroke, older age, higher baseline CI, and higher SBP during the first 24 h." (PMID 34512528, 2021). "The most severe cognitive impairment group (CDR = 3) had the highest proportion of women (68.4%), the lowest mean age (mean = 62.3), the shortest education years (mean = 5.6), and the largest proportion of positive APOE ε4 allele (57.9 %)." (PMID 34225797, 2021). "In addition to assessing p-tau burden, we also examined the effect of APOE status in PART as a predictor for cognitive impairment." (PMID 34353357, 2021). "Regression analyses showed that after accounting for sex, level of education and presence of APOE ε4 allele(s), the association between baseline GDS30 scores and cognitive impairment (p = 0.104), CERAD scores (p = 0.094) and Braak stage (p = 0.060) were no longer significant." (PMID 33176024, 2021). "Along with pathogenic mutations, genetic variants in at least 3 genes, apolipoprotein E (APOE), microtubule-associated protein tau (MAPT), and α-synuclein (SNCA), might play a role in determining susceptibility to cognitive impairment in PD." (PMID 35003622, 2021). "Therefore, future studies are needed to confirm our current findings in larger samples from different ethnics, and the biological mechanisms of cognitive impairments in schizophrenia involved in ApoE rs429358 should also be further studied." (PMID 34135129, 2021). "APOE genotype is known to modulate systemic inflammation and neuroinflammation, and the response to fish oil interventions, in healthy subjects and in patients with cardiovascular and cognitive disorders." (PMID 34604280, 2021). "Thus, APOE-targeted replacement mice have become an important model for examining chemotherapy-induced cognitive impairment." (PMID 34643772, 2021). "A review studying the effects of APOE on cognition also suggested that some of the cognitive deficits seen in ε4 carriers might be related to AD pathology." (PMID 33521872, 2021). "Interestingly, it has been shown that female ApoE-/- mice display greater cognitive impairment than male ApoE-/- mice." (PMID 34349106, 2021). "Smoking could even protect patients with apolipoprotein E positive breast cancer from anticancer-treatment-induced cognitive impairment." (PMID 33858440, 2021). "Fourth, the APOE ε4 allele is a key factor in the onset of AD and MCI; it exerts a remarkable influence on the relationship between the polymorphism of CYP46A1 and the onset of cognitive impairment." (PMID 34054500, 2021).